GDNF (glial cell derived neurotrophic factor)
Diseases named in the same sentence as GDNF in open-access papers (continued):
Sharing a sentence is not in itself a finding about the gene and the disease.
mood disorder (16 papers, 2011 to 2025). A cognitive disorder a disturbance in which the person's mood is hypothesized to be the main underlying feature. "Both GDNF and leptin exert neurotrophin-like actions in the hippocampus, and disturbances in the availability and function of either effector has been implicated in the development of mood disorders." (PMID 33013310, 2020). "The few studies in the literature on GDNF have evaluated its concentration in the peripheral blood of patients with depressive or, more generally, mood disorders." (PMID 39170712, 2024). "Although there are not many studies in the literature relating to the involvement of GDNF in the suicidal phenomenon, there is evidence linking this neurotrophin to the onset of mood disorders." (PMID 39170712, 2024). "We show the brain level of GDNF is higher for the subjects with a mood disorder compared to the control group and brain BDNF is higher in the treated groups." (PMID 34078872, 2021). "Pairwise comparisons showed that GDNF level is—39.9 ± 12 pg/ml, p = 0.0106, was significantly higher than in the brains derived from mood disorders compared to normal controls, —23.8 ± 5.5 pg/ml, p = 0.034." (PMID 34078872, 2021). "Pairwise comparisons showed that GDNF level—39.9 ± 12, p = 0.0106, was significantly higher in the brains from mood disorders compared to normal controls, NC-23.8 ± 5.5, p = 0.034." (PMID 34078872, 2021). "The general linear model results were generated using the formula for the model GDNF (concentration) is predicted by group (control or mood disorder), omitting the intercept." (PMID 34078872, 2021). "Recent studies found that glial cell derived neurotrophic factor promoted development of neurons and played an important role in the pathogenesis of mood disorders." (PMID 26503133, 2016). "Similarly, neuronal cell-related growth factors BDNF and GDNF are also considered to play crucial roles in the fluctuations in neurotransmitters in mood disorders." (PMID 40224600, 2023). "Here we observed GDNF level was significantly greater than NC in the mood disorders group." (PMID 34078872, 2021). "Overall, we demonstrate that blood IL-6, GDNF and BDNF could be informative peripheral biomarkers of brain biology associated with mood disorders, substance disorders, and suicide." (PMID 34078872, 2021). "The association between mood disorders and the monoamine system, especially the dopamine pathways, is well established, however, there are no prior reports on the effect of GDNF polymorphisms on mood characteristics in clinical or non-clinical populations." (PMID 24324616, 2013). "Moreover, the GDNF protein expression was downregulated in the peripheral blood and postmortem brain tissue of patients with mood disorders." (PMID 23304227, 2012). "GDNF is a neurotrophic factor belonging to the transforming growth factor-β (TGF-β) superfamily, which plays a key role in the nervous system, and the pathogenesis of mood disorders." (PMID 39164284, 2024). "However, the finding of increased GDNF in mood disorders and increased BDNF with antidepressant treatment supports a role of growth factors in mood disorder or its medication treatment." (PMID 34078872, 2021).
Obesity (16 papers, 2012 to 2025). Accumulation of substantial excess body fat. "ILC2s also receive multiple inputs from CNS circuits and can also be regulated via PVN-gonadal glial-derived neurotrophic factor (GDNF) to promote energy expenditure and insulin resistance and limit obesity." (PMID 40696355, 2025). "The associations of GDNF with OSA remained after adjustment for BMI, implying that the genetic variants influence susceptibility to OSA through obesity-independent pathways." (PMID 33688499, 2021). "Accordingly, our in vitro experiments, performed under conditions mimicking obesity, revealed a significant increase in GDNF release from EGCs, which was blunted by incubation with the A2BR agonist." (PMID 32443525, 2020). "As a previous study, performed on rat colonic neuromuscular preparations, reported a stimulant effect of GDNF on SP release, we performed a set of in vitro experiments aimed at verifying the occurrence of such interplay in obesity as well." (PMID 32443525, 2020). "GDNF expression and release are markedly increased in the presence of several pathological conditions, including obesity, likely in an attempt at maintaining the integrity of intestinal epithelial barrier and mitigating the inflammatory response." (PMID 32443525, 2020). "We have shown however, that the impact of a secondary insult on renal reserve with obesity, leads to greater renal disease and higher arterial pressures in GDNF HET mice in the early phases of obesity." (PMID 24019901, 2013). "We therefore examined the impact of diet-induced obesity on renal structure and function, and arterial pressure in a genetic model of reduced nephron endowment, the GDNF Heterozygous (HET) mouse." (PMID 24019901, 2013). "This increase in renal collagen concentration with obesity was markedly greater in GDNF HET mice, approximately 25%, compared to WT mice where the increase in collagen concentration with obesity was only 8%." (PMID 24019901, 2013). "Obesity similarly correlated with reduced GDNF levels in ligamentum flavum." (PMID 40722606, 2025). "GDNF transgenic mice are resistant to HFD-induced obesity as well as insulin and leptin resistance." (PMID 32175323, 2020). "We have shown that GDNF has a protective effect on HFD induced obesity and hepatic steatosis." (PMID 32175323, 2020). "Taken together, our results, obtained from colonic tissues isolated from HFD mice and cultured EGCs, point to the concept that enteric glial alterations, occurring in the presence of obesity, sustain both bowel motor dysfunctions and enteric inflammation, through GDNF, SP, and IL-1β release." (PMID 32443525, 2020). "Therefore, it should be very interesting to investigate how GDNF is involved in cancer and obesity pathogenesis." (PMID 27167204, 2016). "Thus, this study aimed to examine the impact of obesity on arterial pressure and renal structure and function in a robust genetic model of low nephron number, the GDNF heterozygous (HET) mice, and in their wild-type (WT) littermates." (PMID 24019901, 2013). "Diet-induced obesity led to a 50% increase in creatinine clearance in WT and GDNF HET mice." (PMID 24019901, 2013). "Obesity led to significant albuminuria in GDNF HET and WT mice." (PMID 24019901, 2013). "Thus, GDNF is a potential therapeutic target for cancer and obesity." (PMID 27167204, 2016). "Since GDNF is clearly another independent key player in angiogenesis, induced by adipose stem cells and cancer cells, it is necessary to further investigate its downstream pathways as this factor may closely be involved in angiogenesis in cancer, obesity, and ischemia injury." (PMID 27167204, 2016). "Together, the findings of GDNF expression by ASC and HCC cells suggest new potential therapeutic targets for cancer and obesity treatments." (PMID 27167204, 2016). "Given the known effects of obesity in the early phase to increase SNGFR, we had anticipated a reduced capacity of the kidneys of GDNF HET mice to undergo further hyperfiltration." (PMID 24019901, 2013).
Obesity (continued). "Recently, with the discovery of GDF15’s specific receptor glial-derived neurotrophic factor (GDNF) receptor alpha-like (GFRAL), enthusiasm is heightened in understanding this hormone’s regulation and exploring its therapeutic application in obesity treatment." (PMID 35202387, 2022). "However whole kidney creatinine clearance increased to similar levels in GDNF HET and WT mice suggesting that the nephrons of the GDNF HET mice were able to mount the appropriate physiological response to obesity." (PMID 24019901, 2013). "CNTNAP2, GLI2, DPT (dermatopontin), AEBP1, ITIH5, CXCL11, GDNF (glial cell derived neurotrophic factor), MCHR1, FLT3, ELANE (elastase, neutrophil expressed), OSMR (oncostatin M receptor) and IL15RA are involved in development of obesity, but these genes might be key for progression of HF." (PMID 34218797, 2021). "Thus, GDNF may be a potential therapeutic target for HCC and obesity treatments." (PMID 27167204, 2016). "Total renal collagen concentration was not different between control WT and GDNF HET mice, but was significantly increased with obesity." (PMID 24019901, 2013).
ischemic stroke (14 papers, 2013 to 2025). A stroke disorder caused by obstruction of blood flow to the brain, due to thrombotic (local blood clot formation) or embolic (due to a blood clot or other material traveling from another site) event. "GDNF potential is promising for translation to treat diseases associated with neuronal death: neurodegenerative disorders, ischemic stroke, and cerebral or spinal cord damages." (PMID 34634077, 2021). "In ischemic stroke rats, neurotrophic factors (glial cell line-derived neurotrophic factor: GDNF; brain-derived neurotrophic factor: BDNF), and vascular endothelial growth factor (VEGF) were upregulated by cortical stimulation." (PMID 25009993, 2014). "The capacity of GDNF to induce axonal growth in neuronal precursors in vivo suggests that it can be used to inhibit neurodegenerative process and prevent neuronal death following ischemic stroke or during neurodegenerative diseases." (PMID 27286696, 2016). "Compared with the vehicle-treated rats, the PJ34-treated rats had more severe neuronal deficits and a larger infarct volume and exhibited fewer activated microglia, greater neuronal loss, decreased GDNF expression and increased TNF-α expression at 3 and 7 days following ischemic stroke." (PMID 23151666, 2013). "Previously we demonstrated that parenchymal stimulation exhibited significant upregulation of GDNF and VEGF for chronic-phase ischemic stroke model of animals." (PMID 25009993, 2014).
peripheral nerve injury (14 papers, 2014 to 2024). Injury to a peripheral nerve. "Exogenous GDNF has been shown to exert positive effects on nerve regeneration and improve functional recovery in the context of experimental peripheral nerve injury." (PMID 38339124, 2024). "The present work shows the synthesis of GDNF-encapsulated CMCht/PAMAM NPs as a nanotool for efficient GDNF delivery to treat peripheral nerve injuries." (PMID 36365226, 2022). "The study by Assunção-Silva demonstrated the use of synthetic Gly-Arg-Gly-Asp-Ser peptide-modified biodegradable gellan gum-based hydrogels enriched with glial derived neurotrophic factor (GDNF)-coated IONPs to treat severe peripheral nerve injury." (PMID 34578651, 2021). "GDNF and NGF are two major neurotrophins that are significantly more effective than other growth factors in promoting axonal regeneration, and a synergistic effect of NGF and GDNF was observed in the treatment of peripheral nerve injury." (PMID 34955758, 2021). "Therefore, various neurotrophic factors, such as NGF, BDNF, and GDNF, have been used to enhance the repair outcomes of peripheral nerve injury." (PMID 33838005, 2021). "Indeed, several studies have shown that exogenous Ret ligand GDNF can prevent neurochemical changes in injured sensory neurons and has an antiallodynic effect on neuropathic pain behaviours induced by peripheral nerve injury." (PMID 24840036, 2014). "However, whether GDNF can ameliorate neuropathic pain in the spinal cord dorsal horn (SCDH) in constriction-induced peripheral nerve injury remains unknown." (PMID 24642655, 2014). "After peripheral nerve injury, several neurotrophic factors, such as BDNF, GDNF, NGF, and neurotrophin-3, are synthesized and secreted by SCs to promote neuroregeneration." (PMID 37071193, 2023). "In this study, CCI-induced peripheral nerve injury did lead to autophagy induction on the SCDH and GDNF prevented the elevated expression of Beclin-1 due to CCI-induced nerve injury." (PMID 24642655, 2014). "For the application of peripheral nerve injuries, chitosan-PCL microspheres for the delivery of GDNF were expected to release therapeutically sufficient quantities of GDNF in a controlled manner." (PMID 25143934, 2014). "GDNF could be a good therapeutic tool to attenuate programmed cell death, including apoptosis and autophagy, consequent to CCI-induced peripheral nerve injury." (PMID 24642655, 2014). "Nerve growth factor (NGF), glial cell line-derived neurotrophic factor (GDNF), brain derived neurotrophic factor (BDNF) and neurotrophin-3 (NT-3) have all been added to biomaterials to treat TBI as well as neurodegenerative disorders spinal cord injuries and peripheral nerve injuries." (PMID 26056586, 2014).
glioblastoma (13 papers, 2012 to 2024). The most malignant astrocytic tumor (WHO grade IV). "The aim of this study was to identify the receptor for glial cell line-derived neurotrophic factor (GDNF) in glioblastoma multiforme (GBM)." (PMID 29088765, 2017). "To analyze the effect of miR-9, miR-96, miR-133b, and miR-146a on endogenous GDNF expression, we transiently overexpressed these miRNAs in U87 cells (a human glioblastoma cell line that expresses endogenous GDNF at detectable levels)." (PMID 26681446, 2015). "Collectively, these observations support the idea that b-PMT effects on RET and GDNF expression could be sufficient to induce the RET-dependent programmed cell death of glioblastoma cells." (PMID 36879662, 2022). "In addition, antidepressant exposure increased GDNF release in a rat C6 glioblastoma cell line, whereas lithium treatment in rats resulted in increased GDNF concentrations in the PFC and occipital cortex but a decrease in the hippocampus." (PMID 29961124, 2018). "Moreover, Rehmannia extract stimulated glial cell-derived neurotrophic factor (GDNF) gene expression in C6 glioblastoma cells, through upregulating cPKC and ERK 1/2 pathways." (PMID 21808655, 2012). "Glial cell line-derived neurotrophic factor (GDNF) is highly expressed in glioblastoma (GBM) and blocking its expression can inhibit the initiation and development of GBM." (PMID 32183903, 2020). "Glial-cell-line-derived neurotrophic factor (GDNF) is highly expressed and is involved in the malignant phenotype in glioblastomas (GBMs)." (PMID 39337713, 2024).
colitis (12 papers, 2011 to 2025). Inflammation of the colon. "In dextran sodium sulphate (DSS)‐induced colitis in mice application of GDNF enhanced recovery as revealed by reduced disease activity index and histological inflammation scores." (PMID 39610047, 2025). "The DSS colitis recovery model was used to assess the potential effects of GDNF on intestinal epithelial integrity and overall recovery of animals with intestinal inflammation." (PMID 39610047, 2025). "Comparable to the observations in DSS‐induced colitis, co‐staining with Ki67 demonstrated a significantly increased number of proliferative cells in the crypts following GDNF treatment compared to controls." (PMID 39610047, 2025). "Daily i.p. application of GDNF (5 μg/kg bodyweight in 100 μL NaCl 0.9%) after colitis‐induction significantly decreased disease severity and increased body weight compared to control animals." (PMID 39610047, 2025). "A comparable observation was made in the acute DSS colitis recovery model when the extent of mucosal lesions and overall inflammation was attenuated after the application of GDNF." (PMID 39610047, 2025). "In trinitro-benzene-sulfonic acid (TNBS)-induced colitis in rats, glial cell line-derived neurotrophic factor (GDNF) protects enteric neurons from cell death due to metabolic challenges by activating HIF-1α and the REarranged during Transfection (RET) pathway." (PMID 38605960, 2024). "The authors showed that treatment of mice with recombinant adenoviruses to overexpress GDNF ameliorated dextran sulfate sodium (DSS)-induced colitis, improved colonic transit defects, and in vitro IEC healing responses." (PMID 37692784, 2023). "Enteric glial cell-derived GDNF was shown to ameliorate inflammation in a mouse model of barrier damage induced colitis." (PMID 37692784, 2023). "In a murine colitis model, GDNF was shown to ameliorate intestinal epithelial barrier function through reducing epithelial permeability and inhibiting mucosal inflammation." (PMID 36028644, 2022). "The expression of GFAP and glial-derived neurotrophic factor (GDNF) in colon biopsies was increased in patients with colitis." (PMID 36340713, 2022). "Thirty-seven (37 = 58.7%) of these DMRs associated with genes, but only 6 (16.2%) of those have been implicated in either colitis (PTPRF, ELTD1, and GDNF) or CRC (PTPRF, ELTD1, PDX1, CCK, and AGPAT1)." (PMID 27006956, 2016). "To test this, we used a mouse model of DSS‐induced colitis and biopsy‐based mucosal wound assays to evaluate whether GDNF application affects mucosal healing and regeneration in vivo." (PMID 39610047, 2025). "In addition, glial cell line-derived neurotrophic factor (GDNF) is downregulated in DSS-induced colitis and during inflammation, and the use of GDNF reduces inflammation." (PMID 38129886, 2023). "Interestingly, GDNF ameliorated experimental colitis, inhibited mucosal inflammatory response and decreased intestinal permeability in the mouse model of colitis induced by dextran sodium sulfate (DSS)." (PMID 34205534, 2021). "Patients with colitis Crohn also had an increase in GFAP and GDNF expression in inflamed colonic biopsies, but less impressive than patients with UC." (PMID 21235736, 2011). "In the present model, GDNF was applied therapeutically since DSS‐induced colitis had been induced first for 5 days before GDNF application which supports the notion that GDNF had regenerative effects rather than inhibitory effects on inflammation‐induced changes." (PMID 39610047, 2025).